RASSF6 (Ras association domain family member 6)
Diseases named in the same sentence as RASSF6 in open-access papers (continued):
Sharing a sentence is not in itself a finding about the gene and the disease.
tumor (17 papers, 2009 to 2025). "It was also reported that Ras association domain family member 6 (RASSF6) as a tumor suppressor inhibits sorafenib resistance by repressing MCL-1 through the JNK-dependent pathway in RCC cells." (PMID 34384473, 2021). "The correlation of tumor abundance as well as PML deficiency as well as downregulated RASSF6 and NLRP12 expression was confirmed in our patient cohort." (PMID 31144474, 2019). "PML‐deficiency in combination with HCV therefore is associated with decreased expression of RASSF6, correlating with increased cell proliferation and tumor growth in vivo and in vitro." (PMID 31144474, 2019). "RASSF6 has been found to be tightly associated with tumorigenesis and functions as a tumor suppressor." (PMID 25028967, 2014). "Furthermore, low RASSF6 expression was significantly associated with tumour size (p = 0.042), TNM stage (p < 0.001), and the presence of distant metastases (p < 0.001)." (PMID 28903410, 2017). "To further confirm our hypothesis that RASSF6 acts as a tumor suppressor, and loss of RASSF6 might be involved in the pathogenesis of sCRC, we performed systematic experiments both in vitro and in vivo." (PMID 27009808, 2016). "The increased expression of RASSF6 by HTac and HT treatments reveals a potential new mechanism of the antitumor effect of HT, encouraging the further study of HTac in tumor interventions." (PMID 37891913, 2023). "Our results indicated that the expression of RASSF6 is significantly decreased in tumour tissues compared with its expression in paired adjacent non-tumour tissues (p < 0.001)." (PMID 28903410, 2017). "Tumours from the RASSF6 group displayed a weaker Ki67 staining intensity compared with that of the control groups, and the expression level of RASSF6 negatively correlated with Ki67 expression (p < 0.05)." (PMID 28903410, 2017). "Low RASSF6 expression was detected in 83 (65.3%) of the resected tumour tissue samples, whereas the remaining 44 cases (34.6%) displayed high levels of RASSF6 expression." (PMID 28903410, 2017). "Classical RASSFs (RASSF1 to RASSF6) encode a C-terminal RA and SARAH domain, which encode tumor suppressors, involved in cell cycle regulation, microtubule stability and apoptosis." (PMID 28903410, 2017). "Results showed that both the weight and volume of tumours were significantly decreased in the RASSF6 group compared with the Vector group." (PMID 28903410, 2017). "Studies of several tumours have shown that RASSF6 expression is downregulated, and low RASSF6 expression corresponds to a poor prognosis." (PMID 28903410, 2017). "Colony formation assay further showed that overexpression of RASSF6 resulted in tumor growth inhibition (*P < 0.05)." (PMID 27009808, 2016). "Further experiments showed exogenous introduction of RASSF6 into LoVo cells suppressed cell proliferation, migration, invasion, and induced apoptosis in vitro as well as tumor growth in vivo." (PMID 27009808, 2016). "Previous reports have shown that, similar to other members of RASSF family, RASSF6 acts as a tumor suppressor." (PMID 27009808, 2016). "Decreased level of RASSF6 was observed in adenocarcinoma compared to normal tissues, especially in advanced tumor cases." (PMID 27009808, 2016). "Compared with the control group, RASSF6-stably expressed cells revealed a decreased tumor size and tumor weight, whereas low RASSF6 level in HT-29 promoted tumor growth as compared to control siRNA group." (PMID 27009808, 2016). "Many, including us, have compared RASSF1A and RASSF6 in their properties as a tumor suppressor, their ability to interact with MDM2, their involvement in TNF-α signaling and inflammation, as well as comparing them with Nore1- in the Ras-induced apoptosis." (PMID 26690221, 2015).
tumor (continued). "If RASSF6 induces apoptosis and regulates the cell cycle independently of the Hippo pathway, how does RASSF6 function as a tumor suppressor?" (PMID 26690221, 2015). "To reach this goal, we need to identify the mechanism of how RASSF6 fulfills its tumor suppressor role and to find out a drug target that surrogates RASSF6." (PMID 26690221, 2015). "Expression of RASSF6 is epigenetically suppressed in human cancers and is generally regarded as a tumor suppressor." (PMID 26690221, 2015). "Rassf6 is being increasingly recognized as an important tumor suppressor that is involved in cellular signaling pathways for cell apoptosis in various cell types including HeLa and MCF-7 cells." (PMID 23626755, 2013). "SiRNA-mediated knockdown of RASSF6 enhances tumourigenic growth in soft agar whilst RASSF6 overexpression reduces tumour growth in a variety of tumour cell lines." (PMID 19570220, 2009). "Given the well-established role of Wnt signalling in the regulation of CRC tumour progression, we hypothesized that RASSF6 influences CRC cell function through the Wnt signalling pathway." (PMID 28903410, 2017). "Moreover, the expression of RASSF6 also significantly decreased in tumour tissues compared with its expression in paired adjacent non-tumour tissues at both mRNA and protein level." (PMID 28903410, 2017). "Moreover, we performed immunohistochemistry to examine the expression patterns of RASSF6 and Ki67, a nuclear cell proliferation marker, in the collected tumours." (PMID 28903410, 2017). "Collectively, our expression results showed decreased level of RASSF6 might be associated with aggressive CRC phenotypes (high metastatic ability cell lines and advanced tumor patients)." (PMID 27009808, 2016). "In this study, we are here for the first time to show RASSF6 screened by whole exome sequencing may serve as a novel candidate against tumor for sCRC." (PMID 27009808, 2016). "RASSF6 may serve as a novel candidate against tumor growth for sCRC." (PMID 27009808, 2016). "Further work is needed to understand the expression patterns of RASSF6 and PTPRG, which are generally considered to be tumor suppressors and genes like BIRC3 and CDKN1A that are known to be involved in a number of different cancers." (PMID 37910143, 2023). "The other cluster including RASSF5, RASSF6, STAT1, CEACAM1, BNIP3L and SOCS2 is related to tumor suppression." (PMID 32201535, 2020). "Based on our results, RASSF6 appears to act as a tumour suppressor in CRC development, and Wnt is a potential mediator for RASSF6-regulated EMT progression." (PMID 28903410, 2017). "Here, we report for the first time that RASSF6 inhibits the EMT process and CRC cell function and tumour progression by suppressing the Wnt signalling pathway." (PMID 28903410, 2017). "For example, RASSF5 methylation highly correlated to MYCN amplification and INRG stage M. Furthermore, high methylation of RASSF6 was correlated to unfavorable outcome, 1p deletion and MYCN amplification in our tumor material." (PMID 22695170, 2012). "RASSF6 and TRIM16L have been identified as tumor-suppressor proteins." (PMID 37891913, 2023). "The levels of RASSF6 immunoreactivity varied between tumour tissue samples and the adjacent non-tumour tissue samples." (PMID 28903410, 2017). "Moreover, RASSF6 directly activates the Hippo pathway by enhancing the phosphorylation of STK4/3 and LATS1/2 kinases, thereby reinforcing its role as a critical upstream activator of Hippo tumor-suppressive signaling." (PMID 41153630, 2025). "Furthermore, considering that several signalling pathways participate in the tumour suppressor role of RASSF6 in other types of tumours, there is a strong possibility that Wnt is not a unique mechanism involved in the RASSF6 regulation of CRC." (PMID 28903410, 2017).
tumor (continued). "Given that RASSF6 inhibiting Wnt signalling in CRC, we suspect that RASSF6 may also involve in other biological processes in CRC, such as stem cell maintenance, angiogenesis, and anti-tumour drug resistance, all of which require further investigation in future studies." (PMID 28903410, 2017). "Interestingly, not only the tumorous tissue but also the tumor‐surrounding tissue of PML−/−HCVtg livers, and PML−/−HCVtg livers without tumor development showed a stepwise decrease in RASSF6 expression." (PMID 31144474, 2019).
cancer (13 papers, 2009 to 2025). A tumor composed of atypical neoplastic, often pleomorphic cells that invade other tissues. "In our previous exome sequencing study, we focused on the LoF mutations that could impair protein expression in sCRC cancer genome, and identified a frameshift mutation of RASSF6 in one sCRC patient." (PMID 27009808, 2016). "MALAT1 has been found to promote cell proliferation and migration of cancer cells by regulating the expression of genes promoting metastases, e.g., RASSF6, HNF4G, CA2, ROBO1, MIA2." (PMID 35887000, 2022). "Methylation of RASSF1, RASSF2, RASSF3, RASSF6, RASSF7, and RASSF9, from the RASSF regulator family was strongly associated with expression of several GMDs in a variety of cancer categories." (PMID 33676569, 2021). "Wound scratch assays and Transwell chamber (Matrigel-free) were performed to check the effect of RASSF6 on cancer cell migration ability." (PMID 27009808, 2016). "Instead, we observed very frequent inactivation of RASSF6 reiterating the importance of several classical RASSF members in the development of different forms of cancer." (PMID 19570220, 2009). "Likewise, RASSF6 was differentially expressed in response to DEX treatment and is suppressed in human cancers and its low expression level is associated with poor prognosis." (PMID 35585182, 2022). "The level of RASSF6 was lower in cancer compared to adjacent normal tissue in 4 out of 5 patients." (PMID 28077118, 2017). "Additionally, we explored the effect of RASSF6 on the invasion ability of cancer cells using a Matrigel invasion assay." (PMID 27009808, 2016). "Also, RASSF6 was shown decreased expression in cancer compared to adjacent normal tissues." (PMID 28077118, 2017). "KEGG pathway analysis further highlighted the role of S6K1 in cancer progression, in which the depletion of S6K1 could re-express a group of tumor suppressor genes including RASSF5, RASSF6, STAT1, CEACAM1, BNIP3L and SOCS2." (PMID 32201535, 2020). "Given that RASSF6 epigenetic inactivation has not previously been observed in any cancer we next sought to determine the extent of methylation across the RASSF6 CpG island and determine whether methylation correlated with loss or downregulation of RASSF6 expression." (PMID 19570220, 2009). "Clinically, low RASSF6 expression correlated with poorer overall survival in patients with luminal A and non-luminal HER2-positive cancers, underscoring its prognostic significance and potential utility as a biomarker of Hippo pathway integrity." (PMID 41153630, 2025).
adenocarcinoma (1 paper, 2016). A common cancer characterized by the presence of malignant glandular cells. "RASSF6 expression was observed in 80.8% (42/52) of the adenocarcinoma cases and 100% (52/52) of the normal cases." (PMID 27009808, 2016). "RASSF6 was highly expressed in benign glands compared with adenocarcinoma, and no strong RASSF6 staining was found in adenocarcinoma cases." (PMID 27009808, 2016).
infection (1 paper, 2024). The state of being infected such as from the introduction of a foreign agent such as serum, vaccine, antigenic substance or organism. "However, q-PCR results only revealed that Rassf1 was significantly up-regulated during PmCQ2 infection, whereas Rassf6 was not significantly changed compared with the wild type." (PMID 38493147, 2024).
RASSF6 also shares sentences with these, for which no sentence is quoted: nasopharyngeal carcinoma (3 papers); pancreatic ductal adenocarcinoma (2); childhood acute lymphocytic leukemia (1); childhood leukemia (1); clear cell renal carcinoma (1); lipoma (1); lung carcinoma (1); lymph node metastasis (1); metastatic melanoma (1); pancreatic cancer (1); periodontitis (1); rectum adenocarcinoma (1); renal cell carcinoma (1); RSV bronchiolitis (1).